CD151 (CD151 molecule (Raph blood group))
Diseases named in the same sentence as CD151 in open-access papers (continued):
Sharing a sentence is not in itself a finding about the gene and the disease.
ovarian carcinoma (6 papers, 2012 to 2021). A malignant neoplasm originating from the surface ovarian epithelium. "Recently, CD151, a master regulator of LB integrin function and signaling, has also been implicated in the progression of ovarian cancer." (PMID 25356755, 2014). "Additional evidence supporting the suppressive role of CD151-α3β1 integrin complexes in ovarian cancer comes from the loss of tumor-promoting molecules within CD151-deficient TEMM, such as CD9 and claudin-3." (PMID 25356755, 2014). "Initially, our FACS analyses indicated that the degree of surface expression of CD151 and its associated LB integrins (α3, α6 and β4) were highly variable between ovarian cancer cell lines, similar to their RGD-based counterparts (e.g., α2β1 or α5β1 integrin)." (PMID 25356755, 2014). "Thus, available observations on the function of CD151 and its associated LB integrins in human ovarian cancer are conflicting and need clarification." (PMID 25356755, 2014). "Moreover, CD151-deficient ovarian cancer cells displayed a 2-8-fold increase in β-catenin and Axin-2 proteins, two key signaling intermediates downstream of the canonical Wnt pathway." (PMID 25356755, 2014). "A similar role has been recently implicated for CD151 in the progression of ovarian cancer." (PMID 25356755, 2014). "Hence, evaluating these CD151-α3β1 integrin complex-associated effectors as new biomarkers may aid in the future detection or diagnosis of human ovarian cancer malignancy." (PMID 25356755, 2014). "Meanwhile, expression of α3 integrin in luminal cells appear unaffected, implicating that the tumor-suppressive role of CD151 in breast, prostate and ovarian cancers are attributed to the combined action of integrin- and self-associated CD151 molecules." (PMID 33919420, 2021). "Building on our previous finding where CD151 removal gave rise to an EMT-like morphology in ovarian cancer cells, we evaluated the state of EMT-inducing factors." (PMID 25356755, 2014). "Our results indicate that CD151-α3β1 integrin complexes suppress ovarian cancer malignancy largely by counteracting EMT-like processes as well as inhibiting Slug activation and canonical Wnt signaling." (PMID 25356755, 2014). "One of the surprising observations from the current study is the inverse functional link between CD151-α3β1 integrin complexes and the signaling of canonical Wnt pathways in ovarian cancer." (PMID 25356755, 2014). "It is also worth noting that the fallopian tube, another site for serous –type ovarian cancer origin, displayed a basal-lateral staining pattern for CD151." (PMID 25356755, 2014). "Taken together, these observations consistently suggest that CD151 plays a suppressive role in ovarian carcinoma growth largely by counteracting Slug-mediated EMT-like process." (PMID 25356755, 2014). "Our analyses of clinical specimens, tumor cell activities and xenograft models support a tumor-suppressive role of CD151-α3β1 integrin complexes in ovarian cancer." (PMID 25356755, 2014). "Since tetraspanin molecules like CD151 are known to function within TEMM, we next evaluated the impact of disrupting CD151 on the integrity of LB integrin-enriched protein complexes in ovarian cancer cells." (PMID 25356755, 2014). "To understand how CD151 regulated Slug in ovarian cancer cells, we turned our attention to Wnt signaling, as it has been strongly connected to the activation of Slug in human carcinomas." (PMID 25356755, 2014). "The known role of CD151 in cell-cell attachment and its potential role in invasion/migration in ovarian cancer led us next to examine the expression of CD151 in ovarian-derived cell lines." (PMID 22272937, 2012). "We identified the transmembrane protein CD151 as being overexpressed in all tumor samples and then demonstrated it to be a potential target to inhibit metastasis and dissemination of ovarian cancer." (PMID 22272937, 2012). "Quantitative RT-PCR revealed that all ascites-derived cell lines and ovarian cancer cells expressed CD151 message." (PMID 22272937, 2012).
ovarian carcinoma (continued). "We next evaluated its role in EOC dissemination using two ovarian cancer-derived cell lines with differential levels of CD151 expression." (PMID 22272937, 2012). "Additionally, it is supported by analyses of CD151 and α3β1 integrin expression in tumor biopsies of lobular or inflammatory breast cancer or colon and ovarian cancer patients." (PMID 33919420, 2021). "In addition to the studied tetraspanins and cell adhesion molecules, the complex of other tetraspanin CD151 and cell adhesion molecule α3β1 integrin suppressed ovarian cancer progression repressing the other signalling pathways." (PMID 32091301, 2020). "In this regard, adhesion complexes, such as CD151-α3β1 integrin, may have a strong impact on ovarian cancer progression and metastasis through controlling cell-cell contact." (PMID 25356755, 2014). "Because E-cadherin-associated cell-cell contacts confer an inhibitory role in ovarian tumor cell growth and dissemination, our data imply that CD151 may suppress ovarian cancer malignancy by stabilizing cell-cell contacts between carcinoma cells." (PMID 25356755, 2014). "Interestingly, in addition to decreased expression of E-cadherin, CD151 removal leads to a marked induction in fibronectin (FN), a strong promoter of ovarian cancer malignancy." (PMID 25356755, 2014). "Aside from genetic factors, the tumor-suppressive role of CD151-α3β1 integrin complexes in ovarian cancer may be related to their roles in maintaining stable cell-cell contact." (PMID 25356755, 2014). "Consequently, our study raises the possibility that CD151-α3β1 integrin complexes impact ovarian cancer malignancy largely by repressing the EMT-like process and potentially the RhoA activation from fibronectin-α5β1 integrin-mediated signaling." (PMID 25356755, 2014). "At the present time, however, how CD151 removal leads to the increased expression or activation of Slug and β-catenin in ovarian cancer remains unclear." (PMID 25356755, 2014). "Moreover, the pro-malignancy factors or pathways counteracted by CD151 and α3β1 integrin may serve as therapeutic targets against ovarian cancer." (PMID 25356755, 2014). "Our data show that intact CD151-α3β1 integrin complexes inhibit the induction of the EMT-like process, a critical driver of ovarian cancer progression and metastasis." (PMID 25356755, 2014). "Collectively, these data indicate a novel signaling cross-talk between CD151 and the canonical Wnt/β-catenin/CBP axis-mediated pathway in ovarian cancer cells." (PMID 25356755, 2014). "We show that in the ovarian cancer cell lines SKOV3 and OVCAR5, CD151 is a functionally important molecule whose silencing or blockade impeded cell migration or invasion to different levels dependent on level of CD151 expression." (PMID 22272937, 2012). "It is also worth noting that there was minimal change in the activation in PI3K/AKT- or RAS/MAPPK-mediated pathways in ovarian carcinoma cells upon CD151 ablation (data not shown)." (PMID 25356755, 2014). "Two other proteins were significantly increased with age including CD151, a tetraspanin that enhances cellular processes involved in tumorigenesis and metastasis and MUCIN16 (also known as CA-125), a well-established circulating marker of ovarian cancer and possibly other types of cancers." (PMID 28465537, 2017).
endometrial cancer (5 papers, 2011 to 2024). Primary or metastatic malignant neoplasm involving the endometrium (mucous membrane that lines the endometrial cavity). "This is the first study to evaluate the staining and prognostic significance of tetraspanin CD151 in endometrial carcinoma." (PMID 21505452, 2011). "In endometrial cancer (EC), the EM2D9 monoclonal antibody may regulate the migration of endometrial cancer cells through a complex of CD151 and α5β1 integrin." (PMID 38279122, 2024). "Although our results strongly suggest that CD151 may have an important role in tumourigenesis in some histology types of endometrial cancer, the mode of its action remains unknown." (PMID 21505452, 2011). "Thus, one possibility might be that CD151 counteracts the metastatic progression of endometrial cancer by stabilizing E-cadherin based cell-cell interactions." (PMID 21505452, 2011). "Our results show that CD151 is an independent marker for DSS and RFS in poor outcome endometrial carcinoma by univariate analysis and for a triple negative subgroup of patients by multivariate analysis." (PMID 21505452, 2011).
epidermoid carcinoma (5 papers, 2013 to 2023). "Utilizing wild type or CD151 ablated A431 epidermoid carcinoma cells, it was shown that the loss of CD151 reduces STAT3 activation in response to 12-O-Tetradecanoylphorbol-13-acetate (TPA) stimulation, which is another known activator of PKCα." (PMID 28428953, 2017). "For example, CD151 promotes migration of epidermoid carcinoma cells via α3β1 and α6β4 integrin-dependent cell adhesion and migration." (PMID 37752807, 2023). "A cross talk has been proposed for hemidesmosomal integrins α6β4 and focal contact-localized integrins α3β1 in epidermal keratinocytes and squamous cell carcinomas involving CD151 and plectin with complex consequences for cell migration." (PMID 27007410, 2016). "Our data showed that patients with high CD151 expression level was associated with poorer overall survival among 150 NSCLC patients, which was consistent with the results in NSCLC subsets, including adenocarcinoma and squamous carcinoma." (PMID 34108040, 2021). "The initial evidence that CD151 promotes metastasis came from a study showing that an antibody with unknown specificity inhibited metastasis formation by a human epidermoid carcinoma line in vivo." (PMID 23533596, 2013). "CD151 is a cell surface glycoprotein belonging to the tetraspanin superfamily that was first shown to promote metastasis in a study in which an unknown antibody specifically inhibited metastasis formation in a human epidermoid carcinoma in vivo." (PMID 23533596, 2013).
ovarian tumors (5 papers, 2012 to 2022). "There was, however, minimal association between CD151 expression and ovarian tumor grade or stage, which contrasts to prior reports on the expression of this protein in other cancer types." (PMID 25356755, 2014). "Intriguingly, we also detected a marked elevation in the expression of KIAA1199 and RNF43 in CD151-deficient ovarian tumor cells, two newly identified negative regulators of Wnt signaling, implying a potential feedback mechanism related to CD151 function." (PMID 25356755, 2014). "In summary, our study demonstrates a suppressive role of CD151 and associated α3β1 integrin in ovarian tumor cell proliferation, growth and ascites production." (PMID 25356755, 2014). "Moreover, consistent with decreased CD151 protein in metastatic tumors was evidence of the heterozygous loss and a marked reduction in mRNA for this gene in the majority of TCGA ovarian tumor samples." (PMID 25356755, 2014). "Hence, we speculate that the increased Slug expression in CD151-deficient ovarian tumor cells may be largely attributed to post-translational regulation." (PMID 25356755, 2014). "Hence, our study for the first time illustrates that CD151-α3β1 integrin complexes and associated pathways regulate ovarian tumor growth and progression and may serve as potential therapeutic targets against this lethal human cancer." (PMID 25356755, 2014). "Together, these observations indicate a significant inverse association between CD151 expression and metastatic status, suggesting a potential suppressive role of CD151 during ovarian tumor progression." (PMID 25356755, 2014). "Collectively, these results provide evidence that CD151 and α3β1 integrin act together to suppress human ovarian tumor growth and dissemination by regulating the integrity of cell-cell contacts among tumor cells." (PMID 25356755, 2014). "Together, our study demonstrates that CD151-α3β1 integrin complexes regulate ovarian tumor growth by repressing Slug-mediated EMT and Wnt signaling." (PMID 25356755, 2014). "In line with a suppressive role of α3 integrin is a trend towards reduced mRNA expression of this gene in ovarian tumors, similar to the prior analysis of CD151." (PMID 25356755, 2014). "Given the strong influence of CD151 ablation on cell proliferation, we next evaluated the role of CD151 in ovarian tumor growth and metastasis by applying ex vivo xenograft models in immunocompromised mice." (PMID 25356755, 2014). "Human tumor tissue arrays (TMA) were adopted for evaluation of the clinical relationship between CD151 and ovarian tumor malignancy." (PMID 25356755, 2014). "Collectively, the marked changes in these important effectors and regulators of Wnt signaling underscore the complex signaling roles of CD151-α3β1 integrin complexes in ovarian tumor growth and progression." (PMID 25356755, 2014). "Xenograft and signaling analyses were then conducted to delineate the functional cascade of CD151-α3β1 integrin complexes during ovarian tumor growth and progression." (PMID 25356755, 2014). "IHC and genomic analyses of human ovarian tumor tissues suggest an inverse correlation between CD151 expression and tumor metastasis." (PMID 25356755, 2014). "Collectively, data from our in vitro and xenograft analyses consistently suggest a strong suppressive role of CD151 in ovarian tumor growth and progression." (PMID 25356755, 2014). "Taken together, our results demonstrate that CD151 and α3β1 integrin act together to suppress ovarian tumor cell growth and malignancy largely by controlling cell-cell contacts, Wnt signaling and Slug activation." (PMID 25356755, 2014). "We therefore tested the notion that CD151 and α3β1 integrin act together to suppress ovarian tumor growth and progression by influencing tumor cell-cell contacts within the tetraspanin-enriched membrane microdomain (TEMM)." (PMID 25356755, 2014).
ovarian tumors (continued). "Since Slug is strongly implicated in regulating epithelial cell proliferation, we next tested if CD151 removal impacted ovarian tumor cell properties in a Slug-dependent manner." (PMID 25356755, 2014). "Next, we investigated the functional role of CD151 using cultured human serous-type ovarian tumor cell lines." (PMID 25356755, 2014). "In our own discovery sample set of EOC tumors, while not reaching statistical significance, we did find an interesting trend of higher CD151 expression in primary ovarian tumors and relatively lower expression in disseminated metastatic or recurrent disease." (PMID 22272937, 2012). "It should be noted that tetraspanin CD151 contributes to survival of a subset of high-grade serous ovarian cancer cell lines associated with a ZEB transcriptional program and supports the growth of ovarian tumors as well." (PMID 36613908, 2022). "Furthermore, E-cadherin expression and cell-cell contacts in ovarian tumor cells were markedly altered upon disruption of CD151 and/or α3β1 integrin." (PMID 25356755, 2014). "Notably, a moderate or strong degree of expression of CD151 was detected in 58% of primary ovarian tumors, but in < 10% of metastatic tumors (p < 0.0055)." (PMID 25356755, 2014). "Furthermore, CD151 – mostly characterised as a tumour‐ and metastasis‐promoting tetraspanin 53 – was also reported to build a complex with the α3β1 integrin, suppressing ovarian tumour growth by inhibiting Slug‐dependent EMT and supporting cell–cell adhesion." (PMID 30982971, 2019). "CD151 staining intensity and localization in normal OSE and ovarian tumor cells also varies." (PMID 22272937, 2012). "Conceivably, CD151 may regulate ovarian tumor growth and dissemination, at least in part, by sequestering the function of tumor-promoting molecules such as CD9 and claudin-3 within the TEMM in ovarian tumor cells." (PMID 25356755, 2014).
pancreatic cancer (5 papers, 2012 to 2024). "Tspan8 has been identified as a biomarker for pancreatic cancer, and its co-localization with CD151-α6β4 has been associated with decreased adhesion and enhanced motility of pancreatic cancer cells." (PMID 38389703, 2024). "Importantly, CD151 appears to be a key player in maintenance of tumor-initiating cells in breast, prostate, and pancreatic cancers, that is, CSCs, as CD151-null/deficient ER+ tumor cells seem unable to sustain the population under in vitro culture." (PMID 33919420, 2021). "Several other proteins in this group also displayed greater induction under serum-free conditions (NOL3, NCS1, CD151), suggesting synergistic effects of hypoxia and nutrient deprivation on pancreatic cancer cell development and angiogenic activity." (PMID 31666928, 2019). "A role for CD151 in cell migration and invasion is consistent through many cancer types including breast, prostate, colorectal, and pancreatic cancers." (PMID 22272937, 2012). "Similarly, CD151 of sEVs secreted by pancreatic cancer cells was found to promote the metastasis of pancreatic cancer in rats through activating stromal cells and increasing the expression of inflammatory cytokines in hematopoietic cells." (PMID 34094979, 2021).
renal cell carcinoma (5 papers, 2010 to 2022). "However, the function of CD151 and its underlying mechanism in renal cell carcinoma is still unknown." (PMID 29568359, 2018). "We found that CD151 was upregulated in renal cell carcinoma tissues and cells and its expression was significantly associated with tumor stage (p=0.019) and survival (p=0.001) by analyzing tissue microarrays." (PMID 29568359, 2018). "It was previously reported that TGFβ1 upregulation after CD151 silencing could revive malignancy, suggesting that CD151 may promote renal cell carcinoma partially by regulating TGFβ1 amounts and inducing TGFβ1/Smad signaling." (PMID 33767593, 2021).